IER3IP1 (immediate early response 3 interacting protein 1)
Description:
Regulator of endoplasmic reticulum secretion that acts as a key determinant of brain size. Required for secretion of extracellular matrix proteins. Required for correct brain development by depositing sufficient extracellular matrix proteins for tissue integrity and the proliferation of neural progenitors. Acts as a regulator of the unfolded protein response (UPR) (By similarity).
Synonyms: HSPC039; MEDS; PRO2309
Tractability: Antibody: UniProt predicts a signal peptide or a membrane-spanning region. PROTAC: ubiquitination databases record sites on it; its protein half-life has been measured.
Gene: Protein-coding gene on chromosome 18 (47,152,834 to 47,176,381, reverse strand). Ensembl gene ENSG00000134049.
Subcellular location: Endoplasmic reticulum membrane
Subcellular location (Human Protein Atlas): Endoplasmic reticulum
Gene Ontology:
Molecular function: protein binding
Biological process: brain development; mitotic cytokinesis; organ growth; positive regulation of extracellular matrix constituent secretion; positive regulation of protein secretion; regulation of fibroblast apoptotic process; endoplasmic reticulum to Golgi vesicle-mediated transport
Cellular component: cytoplasmic vesicle; endoplasmic reticulum; endoplasmic reticulum membrane; membrane; COPII-coated ER to Golgi transport vesicle; Golgi membrane
Genetic constraint (gnomAD): Loss-of-function variants: 15 observed, 10.53 expected, observed/expected ratio (o/e) 1.42, 90% interval 0.94 to 1.9. The upper end of that interval is the gene's LOEUF score, 1.9, which puts it in group 6 of 6, group 1 being the genes least tolerant of losing a copy. Missense variants: 79 observed, 77.89 expected, observed/expected ratio (o/e) 1.01, 90% interval 0.85 to 1.22. Synonymous variants: 36 observed, 31.57 expected, observed/expected ratio (o/e) 1.14, 90% interval 0.87 to 1.51.
Homologues: Orthologues: chimpanzee IER3IP1 (100% identical), guinea pig IER3IP1 (100% identical), pig IER3IP1 (100% identical), dog IER3IP1 (98% identical), macaque IER3IP1 (98% identical), mouse Ier3ip1 (98% identical), rabbit IER3IP1 (98% identical), tropical clawed frog ier3ip1 (90% identical), zebrafish ier3ip1 (78% identical), Drosophila melanogaster CG32069 (52% identical), Caenorhabditis elegans W09G3.8 (49% identical).
Diseases named in the same sentence as IER3IP1 in open-access papers:
IER3IP1 is named in the same sentence as 19 diseases in open-access papers, as found by Europe PMC text mining. Sharing a sentence is not in itself a finding about the gene and the disease. The quoted sentences say what the papers report.
microcephaly (10 papers, 2012 to 2025). A congenital or acquired developmental disorder in which the circumference of the head is smaller than normal for the person's age and sex. "IER3IP1 variants cause microcephaly by dysregulating the secretion of extracellular matrix proteins and key proteins for neuronal development and survival." (PMID 40924476, 2025). "Missense mutations in IER3IP1 (immediate early response-3 interacting protein-1) lead to a Wolcott-Rallison-like syndrome characterized by microcephaly with simplified gyration, epilepsy, and neonatal diabetes." (PMID 28951826, 2017). "Homozygous mutations in the IER3IP1 gene encoding the immediate and early response 3 interacting protein 1 result in infantile diabetes and congenital microcephaly with simplified gyration, hypotonia, intractable seizures, and early death." (PMID 24204302, 2013). "The patients with IER3IP1 mutations presented with more severe microcephaly, permanent neonatal diabetes, and skeletal deformities as compared with patients harboring EIF2AK3 mutations." (PMID 22991235, 2012). "Microcephaly, epilepsy, and diabetes syndrome-1 (MEDS1, OMIM #614231) is an autosomal recessive neurodevelopmental disorder characterized by microcephaly, simplified gyral pattern, severe epilepsy, and early-onset infantile diabetes mellitus caused by mutations in the IER3IP1 gene." (PMID 39115595, 2024). "Therefore, EIEE and microcephaly appear to be pronounced in MEDS caused by mutations in IER3IP1." (PMID 22991235, 2012). "In conclusion, while our study provides valuable insights into IER3IP1's role in neurodevelopment and microcephaly, addressing these limitations through further research will enhance our understanding of the intricate molecular mechanisms involved." (PMID 39115595, 2024). "The third complex subunit, Yif1p, has two human orthologues, YIF1A and YIF1B, andYIF1B mutations can also cause microcephaly and epilepsy, suggesting common pathomechanisms of the YIPF5,YIF1B and IER3IP1 disease-causing variants." (PMID 39115595, 2024). "Another connection between ER stress and MERC metabolic signaling is revealed in the syndrome of microcephaly, epilepsy, and permanent neonatal diabetes (MEDS, MIM#614231), which is based on mutations within the immediate early response 3 interacting protein 1 (IER3IP1) gene." (PMID 39070058, 2024). "This study also characterized a mutation in the Immediate Early Response 3 Interacting Protein 1 (IER3IP1) gene that have not been previously linked to microcephaly." (PMID 37101616, 2023).
epilepsy (9 papers, 2012 to 2025). A brain disorder characterized by episodes of abnormally increased neuronal discharge resulting in transient episodes of sensory or motor neurological dysfunction, or psychic dysfunction. "An epilepsy gene panel identified bi-allelic variants, c.239T > G (p.Leu80*) and c.2T > A (initiator codon), in IER3IP1 that were subsequently shown to be inherited in trans." (PMID 37689631, 2023). "Mutations in the IER3IP1 gene were connected to severe dysfunctions in CNS, and the symptoms include epilepsy." (PMID 32886284, 2020). "Mutations in the IER3IP1 (Immediate Early Response-3 Interacting Protein 1) gene can give rise to MEDS1 (Microcephaly with Simplified Gyral Pattern, Epilepsy, and Permanent Neonatal Diabetes Syndrome-1), a severe condition leading to early childhood mortality." (PMID 39115595, 2024). "Microcephaly, epilepsy, and diabetes syndrome (MEDS) is a congenital disorder with two known etiological genes, IER3IP1 and YIPF5." (PMID 40924476, 2025).
diabetes (7 papers, 2013 to 2024). "Clinical studies have demonstrated that neonates with mutations in IER3IP1 develop early-onset permanent diabetes." (PMID 28915629, 2017). "In addition, a novel frame shift mutation p.Phe27fsSer25 and a p.Val21Gly (V21G) mutation in IER3IP1 were found in a neonatal diabetes patient." (PMID 28915629, 2017). "Among these interactors, EIF2AK3, GLIS3, IER3IP1, and PLAGL1 are linked to Diabetes mellitus in Swiss-Prot." (PMID 34715892, 2021). "Other ER-resident proteins implicated in monogenic diabetes include mesencephalic astrocyte-derived neurotrophic factor (MANF) and immediate early response 3 interacting protein 1 (IER3IP1); they may directly or indirectly modulate the UPR." (PMID 33967960, 2021). "Our study does not delve into certain aspects of MEDS1, such as juvenile diabetes implications and the specific role of malfunctioning IER3IP1." (PMID 39115595, 2024).
chordoma (1 paper, 2023). Chordomas are rare malignant tumors arising from embryonic remnants of the notochord in axial skeleton. "Several candidate genes, including OTUD5, CDK6, LUC7L2, IER3IP1, and HEATR3, were not linked to other chordoma dependency genes following either of these two approaches." (PMID 37024492, 2023).
insulinoma (1 paper, 2017). "In order to determine if there is a molecular link between IER3IP1 deficiency and β-cell survival and proliferation, we knocked down Ier3ip1 gene expression in mouse MIN6 insulinoma cells." (PMID 28915629, 2017).
Microcephaly Epilepsy Diabetes syndrome (1 paper, 2025). "IER3IP1 is associated with brain development and, when mutated, gives rise to developmental abnormalities including Microcephaly Epilepsy Diabetes syndrome (MEDS)." (PMID 40425816, 2025).
neonatal diabetes mellitus (1 paper, 2017). Neonatal diabetes mellitus presents as hyperglycemia, failure to thrive and, in some cases, dehydration and ketoacidosis which may be severe with coma, in a child within the first months of life. "Mutations in the gene for Immediate Early Response 3 Interacting Protein 1 (IER3IP1) cause permanent neonatal diabetes mellitus in human." (PMID 28915629, 2017).
pancreatic cancer (1 paper, 2017). "IER3IP1 may be a potential target for pancreatic cancer treatment." (PMID 28915629, 2017).
infection (1 paper, 2017). The state of being infected such as from the introduction of a foreign agent such as serum, vaccine, antigenic substance or organism. "After infection with IER3IP1 shRNA lentivirus, the proportion of PI staining positive cells increased from 52 ± 3% on day 4 to 72 ± 2% on day 5 and 86 ± 2% on day 6 (all P<0.001), respectively." (PMID 28915629, 2017). "The mRNA levels of IER3IP1 were significantly reduced to 24 ± 1% of control cells on day 4 after infection with lentiviral IER3IP1 shRNA (not shown) and IER3IP1 protein levels were decreased to 22 ± 2% of control." (PMID 28915629, 2017).
mitochondrial disease (1 paper, 2018). "In another patient, who was classified as mitochondrial based on the classical mitochondrial disease symptoms involved, the functionally uncharacterized IER3IP1 gene was identified." (PMID 30369941, 2018). "In an additional patient, the functionally uncharacterized IER3IP1 gene was likely to explain a seemingly mitochondrial disease phenotype, yet no OXPHOS measurement was performed in this patient." (PMID 30369941, 2018).
neurodevelopmental disorder (1 paper, 2025). A behavioral and cognitive disorder with onset during the developmental period that involves impaired or aberrant development of intellectual, motor, or social functions. "In the RVFV GWAS, one SNP above the suggestive significant threshold mapped to the IER3IP1 gene, mutations of which cause a neurodevelopmental disorder in humans, and it was recently demonstrated to play a fundamental role in B-cell development in mice." (PMID 40342962, 2025).
IER3IP1 also shares sentences with these, for which no sentence is quoted: bladder cancer (1 paper); deafness (1); hypothyroidism (1); immune dysfunction (1); kidney disease (1); Obesity (1); permanent neonatal diabetes (1); Vanishing White Matter disease (1).